RNU6-1228P (RNA, U6 small nuclear 1228, pseudogene)
Gene: Small nuclear RNA gene on chromosome 9 (75,198,071 to 75,198,177, forward strand). Ensembl gene ENSG00000212316.
Homologues: Orthologues: chimpanzee U6 (100% identical), macaque U6 (88% identical). Paralogues in human: RNU6-204P (82% identical), RNU6-454P (81% identical), RNU6-1083P (80% identical), RNU6-268P (80% identical), RNU6-652P (80% identical), RNU6-1050P (79% identical), RNU6-1209P (79% identical), RNU6-1310P (79% identical), RNU6-183P (79% identical), RNU6-302P (79% identical), RNU6-336P (79% identical), RNU6-1020P (79% identical), and 1288 more.